PVT1 (Pvt1 oncogene)
Diseases named in the same sentence as PVT1 in open-access papers (continued):
Sharing a sentence is not in itself a finding about the gene and the disease.
gastric cancer (continued). "Two binding sites for FOXM1 (a transcriptional factor that promotes oncogenesis) was found on the promoter region of PVT1 in gastric cancer cells." (PMID 32117705, 2020). "In good agreement, PVT1 is negatively correlated with miR-152 expression in tumors from gastric cancer patients, and its genetic manipulation in SGC7901 and BGC823 gastric cell lines influences miR-152 levels and ultimately, CD151 and FGF2 expression." (PMID 32083000, 2020). "For instance, lncRNA plasmacytoma variant translocation 1 (PVT1) activates STAT3, which leads to an upregulation of VEGF in gastric cancer." (PMID 32992718, 2020). "Several studies have investigated the expression of PVT1 in colorectal and gastric cancer patients treated with different regimens." (PMID 32083000, 2020). "Recent evidence further indicates that PVT1 exhibits aberrant expression in nonsmall-cell lung cancer, cervical cancer, colorectal cancer, and gastric cancer." (PMID 31320749, 2020). "miR-152 expression is downregulated in gastric cancer tissues, most likely as a result of the interaction with PVT1 which has been shown in vitro to effectively sponge this miRNA." (PMID 32083000, 2020). "PVT1 regulated oral squamous cell carcinoma by sponging miR-28-5p, and non-small cell Lung cancer by sponging miR-17-5p or miR-526b, and gastric cancer cells by sponging miR-125, and gallbladder by sponging miR-143." (PMID 33188158, 2020). "Gastric cancer cell lines with PVT1 overexpression show increased HIF-1α mRNA and protein levels, that are reduced with a miR-186 mimic." (PMID 32083000, 2020). "In gastric cancer, miR-186 which binds directly to PVT1 exon 2 through complementary base coupling reduced the expression of the tumorigenic marker HIF-1a." (PMID 32117705, 2020). "The data from this study showed overexpression of PVT-1 can suppress gastric cancer cells sensitivity to 5-FU by increasing Bcl-2 leading to an anti-apoptotic effect." (PMID 35582574, 2019). "A knockdown of PVT1 via short interfering RNA (siPVT1) resulted in decreased cell viability in prostate cancer, melanoma, glioblastoma, gastric cancer, clear cell renal cell carcinoma, breast cancer, and colorectal cancer cell lines." (PMID 31249809, 2019). "Both molecules were analyzed in colorectal and gastric cancers to see how they change with PVT1 knockdown and overexpression." (PMID 31249809, 2019). "These drugs provide a possibility for chemotherapy related clinical applications, and studies have indicated that knocking out PVT1 can reverse multidrug resistance in gastric cancer and colorectal cancer." (PMID 31497532, 2019). "The role of PVT1 in the cell cycle is demonstrated in studies showing that knockdown of PVT1 expression in gastric cancer cells, melanoma cells, and ccRCC significantly induced G0/1 arrest and reduction in S phase." (PMID 31249809, 2019). "Du’s group found patients with late-stage gastric cancer have elevated levels of lncRNA-PVT-1, which coincides with previous studies showing PVT-1’s ability to regulate 5-FU sensitivity." (PMID 35582574, 2019). "An inverse association was observed between PVT1 and miR-186 expression levels which was observed in gastric cancer and hepatocellular cancer, while PVT1 functions as an endogenous ‘sponge’ by competing for miR-448 in pancreatic cancer." (PMID 30083911, 2019). "Knocking down PVT1 in gastric cancer and osteosarcoma significantly increased cisplatin sensitivity and reversed drug resistance to doxorubicin and cisplatin in resistant cell lines." (PMID 31249809, 2019). "PVT1 overexpression has been demonstrated in pancreatic cancer, lung cancer, gastric cancer, and is related to poor prognosis in most of these cases." (PMID 31877167, 2019). "We confirmed that PVT1 can regulate the expression of Bcl2 and enhance drug-resistance of gastric cancer to 5-Fu." (PMID 31205469, 2019).
gastric cancer (continued). "Flow cytometry assay and TdT-mediated dUTP Nick-End Labeling staining were conducted to explore the effects of PVT1 on gastric cancer cell apoptosis." (PMID 31205469, 2019). "Recent results revealed that the long non-coding RNA (lncRNA) PVT1 (long non-coding RNA encoded by the human PVT1 gene) binds STAT3 and protects it from ubiquitin-dependent degradation in gastric cancer." (PMID 31557897, 2019). "Our results showed that PVT1 can inhibit the apoptosis and enhance the 5-Fu resistance of gastric cancer through the activation of Bcl2." (PMID 31205469, 2019). "PVT1 has been implicated in DR and MDR in many cancer types, including gastric cancer, colorectal cancer, and osteosarcoma." (PMID 31249809, 2019). "In another study, expression level of PVT1 was also found to be abnormally increased in gastric cancer patients, and abnormal expression of PVT1 showed promising diagnostic and prognostic values for this disease." (PMID 29760583, 2018). "LncRNA PVT1 plays a role as oncogene in the development of various types of malignant tumors, such as non-small cell lung cancer, gastric cancer and so on." (PMID 29760583, 2018). "The upregulation of circ-PVT1 and downregulation of circ-LARP4 in gastric cancer are independent prognostic factors, and circ-PVT1 overexpression predicts better OS and DFS." (PMID 30064463, 2018). "PVT1 has been explored in numerous pathological processes, including colorectal cancer 43, diabetic nephropathy 44 and gastric cancer." (PMID 29193797, 2018). "PVT1 is upregulated in gastric cancer and high level of PVT1 predicts poor prognosis in GC patients." (PMID 29970131, 2018). "In gastric cancer, high PVT1 expression is an independent prognostic marker for poor overall survival (OS) and disease-free survival (DFS)." (PMID 29244840, 2017). "Higher PVT1 expression indicates a poor prognosis of gastric cancer patients and contributes to cell proliferation through epigenetically regulating p15 and p16." (PMID 29221147, 2017). "And those results found that there was a significant relationship between PVT1 overexpression and poor overall survival of patients with gastric cancer, gynecology cancer and lung cancer." (PMID 29348896, 2017). "The results found a significant relationship between TMN stage and PVT1 expression in gastric cancer (OR = 2.54, 95% CI: 1.70–3.79), hepatocellular carcinoma (OR = 1.75, 95% CI 1.05–2.90) and lung cancer (OR = 3.62, 95% CI 2.00–6.54)." (PMID 29348896, 2017). "For example, PVT1 is significantly up‐regulated in gastric cancer tissues, and increased PVT1 predicted poor prognosis." (PMID 29047230, 2017). "For example, silencing PVT1 which overexpressed in gastric cancer cells can reduce the cisplatin resistance." (PMID 27966450, 2017). "Our results also indicated that increased PVT1 expression significantly related with TMN stages in gastric cancer, HCC and lung cancer, and predicted high incidence of lymph node metastasis and distant metastases in lung cancer." (PMID 29348896, 2017). "Although PVT1 overexpression acted as a safe prognostic factor for tumor size of gastric cancer, it predicted the high incidence of distant metastases in gastric cancer." (PMID 29348896, 2017). "Some studies suggested that overexpression of PVT1 exhibited the anti-apoptotic property and promoted the development of multidrug resistance in gastric cancer and ovarian cancer." (PMID 29348896, 2017). "Recent studies reveal that PVT1 is overexpressed in multiple cancers and correlated with cancer progression, including colorectal cancer 24, gastric cancer 25, and cervical cancer." (PMID 29047230, 2017). "In particular, the results also found that PVT1 was a safe prognostic factor for gastric cancer (OR = 0.72, 95% CI: 0.45–1.14)." (PMID 29348896, 2017).
gastric cancer (continued). "Other study reported that PVT1 promotes cell proliferation through epigenetically regulating p15 and p16, and higher PVT1 expression in gastric cancer was positively correlated with deeper invasion depth and advanced TNM stage." (PMID 29348896, 2017). "To date, siRNA-mediated knockdown strategies targeting PVT1 have demonstrated its role in cisplatin sensitivity in malignant pleural mesothelioma and gastric cancer cells." (PMID 27232880, 2016). "Recent research indicated that upregulation of PVT1 inhibited apoptosis in gastric cancer cell lines, increased the expression of MDR1, MRP, mTOR, and HIF‐1α, promoted the development of multidrug resistance." (PMID 27794184, 2016). "In gastric cancer cells, PVT1 acts to repress the expression of p15 and p16 via its physical interaction with the polycomb group protein, EZH2." (PMID 27232880, 2016). "Next, we examined the correlation of PVT1 expression level with patients’ clinical features in gastric cancer." (PMID 25890171, 2015). "In order to validate our expression data for INK4/ARF TS, we collected the expression profile of the lncRNA PVT1 in UC cell lines, which was very recently reported to repress expression of genes encoded by the INK4 locus in gastric cancer." (PMID 29861427, 2015). "To investigate the role of PVT1 in gastric cancer progression, we detected the PVT1 expression levels in 80 paired gastric cancer tissues and corresponding non-tumor tissues by using qRT-PCR, and normalizing to GAPDH." (PMID 25890171, 2015). "PVT1 knockdown also inhibited gastric cancer cell migration." (PMID 40778107, 2025). "In addition, knockdown of circ-PVT1 enhanced the sensitivity of paclitaxel-resistant gastric cancer cells to paclitaxel." (PMID 35089117, 2022). "In gastric cancer (GC), circ-PVT1 downregulation impaired chemotherapy resistance to paclitaxel." (PMID 36358938, 2022). "Similarly,it has already been reported in anothor study that lncRNA PVT1 inhibite the proliferation of gastric cancer by combining with enhancer of zeste homolog 2 (EZH2) to repress p15 and p16." (PMID 35392800, 2022). "By interacting with FOXM1, PVT1 promoted gastric cancer progression." (PMID 35592755, 2022). "They showed that PVT1 has three potential binding sites for miR-152 and that PVT1 may act as a “sponge” to inhibit miR-152 in gastric cancer." (PMID 34940760, 2021). "lncRNA PVT1 might act as a novel predictive biomarker of poor prognosis and clinicopathological characteristics for gastric cancer." (PMID 34900027, 2021). "Moreover, PVT1 can regulate forkhead box M1 (FOXM1) to facilitate gastric cancer growth and invasion." (PMID 32156248, 2021). "Notably, PVT1 enhanced Bcl2 expression in gastric cancer cells, thereby inhibiting apoptosis and promoting resistance to 5-fluorouracil." (PMID 34564701, 2021). "PVT1 is also transcriptionally activated by FOXM1 in gastric cancer." (PMID 31320749, 2020). "Of interest, PVT1 locus leads to the production of a cluster of four annotated miRNAs, namely miR-1204, miR-1205, miR-1206, and miR-1207 (-5p and -3p), being some of them important in the tumorigenic process of colorectal and gastric cancer." (PMID 32083000, 2020). "For example, both SNHG20 and PVT1 are related to stomach cancer." (PMID 33318305, 2020). "PVT1 has been shown to interact with transcription factor STAT3 in gastric cancer cell lines." (PMID 32083000, 2020). "Another miRNA, miR-152 was found to be negatively correlated with PVT1 in gastric cancer tissues." (PMID 32117705, 2020). "PVT1 negatively regulates the expression of p15 and p16 and its inhibition may contribute to cell-cycle arrest in gastric cancer." (PMID 32117705, 2020). "To date, several lncRNAs, including RMRP, AA174084, PVT1, H19, LINC00982, ABHD11-AS1 (ABHD11 antisense RNA 1), UCA1 (urothelial cancer associated 1), and LINC00152 have been identified from gastric juice and demonstrated as biomarkers for gastric cancer." (PMID 32460771, 2020).
gastric cancer (continued). "Interestingly, miR-1207-5p miRNA seems to exhibit oncogenic activity in colorectal cancer while having tumor suppressor effects in gastric cancer cells (contrary to the oncogenic role of PVT1)." (PMID 32083000, 2020). "PVT1 is a widely reported oncogene that may be involved in renal cancer, lung cancer, colorectal cancer, gastric cancer, hepatocellular carcinoma, ovarian cancer, and leukaemia 21-24." (PMID 32368310, 2020). "For example, the lncRNA PVT1 regulates malignant behavior in xenograft models of breast cancer cells, whereas small nucleolar RNA host gene 5 knockdown restrains the malignant phenotype of gastric cancer cells by targeting the miR-32/KLF4 axis." (PMID 31789416, 2020). "Additionally, the overexpression and regulatory effects of PVT1 in human tumors, such as cervical cancer, prostate cancer, melanoma, and gastric cancer, have been described." (PMID 31497532, 2019). "Studies have shown that PVT1 is expressed at low levels in normal tissues, while it is highly expressed in various malignant tumors and tumor cell lines, such as gastric cancer, lung cancer, hepatocellular carcinoma, thyroid carcinoma, breast cancer, and pancreatic cancer." (PMID 31309249, 2019). "Notably, advanced TNM stage significantly correlated with increased PVT1 expression in ccRCC and gastric cancer." (PMID 31249809, 2019). "However, in gastric cancer, it was reported that overall and disease-free survival was highest with increased circPVT1 expression and decreased PVT1 expression, and lowest with the reverse." (PMID 31249809, 2019). "We confirmed that PVT1 can promote the progression of gastric cancer." (PMID 31205469, 2019). "In gastric cancer cells, whether PVT1 is related to these molecules and its functions are undefined." (PMID 30679629, 2019). "Moreover, PVT1 knockdown has been previously illustrated to result in decreased PCNA expression in gastric cancer cells which was found to inhibit cell proliferation." (PMID 31303891, 2019). "High FOXM1 expression in gastric cancer significantly induces PVT1 expression." (PMID 29113415, 2017). "Thus, high expression of FOXM1 and PVT1 form a positive feedback loop that promotes gastric cancer proliferation and metastasis." (PMID 29113415, 2017). "Knockdown of PVT1 could reverse cisplatin-resistance in the resistant gastric cancer cells by regulating the expression of MDR1, MRP, mTOR and HIF-1α." (PMID 29108264, 2017). "The results found that there was a significant relationship between PVT1 overexpression and poor OS of patients with gastric cancer (HR = 1.63, 95% CI: 1.09–2.17, P < 0.001), gynecology cancer (HR = 1.33, 95% CI: 1.08–1.57, P < 0.001) and lung cancer (HR = 1.94, 95% CI: 1.31–2.57, P < 0.001)." (PMID 29348896, 2017). "As a highly conserved lncRNA, PVT1 has attracted great attention due to its critical and various functions in many cancers, including cervical cancer, ovarian cancer, hepatocellular carcinoma, pancreatic cancer, gastric cancer, lung cancer, and breast cancer." (PMID 28265576, 2017). "In our study, we showed high abundance binding between PVT1 and EZH2 in gastric cancer cells, and we further confirmed that PVT1 could mediate epigenetic regulation of p15 and p16 in Trans." (PMID 25890171, 2015). "Importantly, we first reported that PVT1 serving as a member of PRC2-mediated epigenetic regulation participated in the development of gastric cancer." (PMID 25890171, 2015). "Together, these results suggest that lncRNA PVT1 may serve as a candidate prognostic biomarker and target for new therapies in human gastric cancer." (PMID 25890171, 2015). "However, the possible role and molecular mechanism of PVT1 in human gastric cancer remains to be clarified." (PMID 25890171, 2015). "Our results showed that PVT1 knockdown could significantly inhibit gastric cancer cell proliferation both in vitro and in vivo." (PMID 25890171, 2015).
gastric cancer (continued). "Together, these results indicate that lncRNA PVT1 plays a critical role in gastric cancer and may serve as a candidate target for new therapies in human gastric cancer." (PMID 25890171, 2015). "PVT1 is overexpressed in gastric cancer and promotes cell growth through repressing p15 and p16." (PMID 26517688, 2015). "PVT1 may be a promising target for new gastric cancer therapy." (PMID 35592755, 2022). "Similarly, lncRNA PVT1 was verified to function as a tumor promoter in gastric cancer." (PMID 34179148, 2021). "In addition, lncRNA PVT1 promotes angiogenesis via STAT3/VEGFA axis in gastric cancer." (PMID 32600379, 2020). "Additionally, oncogenic lncRNAs MALAT1 and PVT-1 could contribute to 5-FU resistance of gastric cancer by modulating expression of the miR-23b-3p/ATG12 axis and Bcl-2, respectively." (PMID 32192494, 2020). "In addition, circRNA circ-PVT1 could facilitate paclitaxel (PTX) resistance of gastric cancer cells via up-regulating ZEB1 mediated by miR-124-3p." (PMID 32192494, 2020). "However, the underlying molecular mechanisms of PVT1 in gastric cancer (GC) remain largely unknown." (PMID 31205469, 2019). "Circular RNA circ-PVT1 has been discovered to upregulate the gene expression in the gastric cancer (GC) tissues and promotes the GC cells reproduction." (PMID 31608124, 2019). "PVT1 might serve as an independent prognostic biomarker for gastric cancer patients." (PMID 29108264, 2017). "Amplification of PVT1 contributes to the aggressive pathophysiology of ovarian and breast cancer and overexpression of PVT1 is a powerful predictor of tumor progression and overall survival in patients with diverse types of cancer, including gastric cancer and colorectal cancer." (PMID 28404954, 2017). "In the current study, we showed that PVT1 was markedly increased in gastric cancer tissues compared with adjacent non-tumor tissues and could be served as an independent predictor for overall survival in gastric cancer." (PMID 25890171, 2015). "Besides, PVT1 promotes progression of gastric cancer and hepatocellular carcinoma." (PMID 26517688, 2015). "This interaction, along with the downregulation of lncRNA PVT1 and the upregulation of BNIP3 levels, inhibited the proliferation of gastric cancer cells, and clinical evidence demonstrates that BNIP3 upregulation favors the prognosis of cancer patients." (PMID 38397398, 2024). "The relationship between the expression of PVT1, hesa-miR-130a-3p and RECK and the prognosis of clinical-pathological features of gastric cancer was further analyzed." (PMID 37255541, 2023). "It was also reported that PVT1 activates CD151 and FGF2 expression through suppression of miR-152 in gastric cancer." (PMID 36624401, 2023). "Several of the induced lncRNAs, such as MALAT1, PVT1, and XIST, have also been shown to have specific properties in gastric cancer and were also identified as upregulated in NPC (25, –, 27)." (PMID 35435703, 2022). "VEGF expression is increased by STAT3 activation through lincRNAs PVT1 and FLANC and hence, angiogenesis rises in gastric cancer (GC) and CRC, respectively." (PMID 32992718, 2020). "STAT3 overexpression in gastric cancer cell lines leads to increased PVT1 levels, while STAT3 knockdown results in PVT1 transcriptional downregulation." (PMID 32083000, 2020). "It has further been shown that silencing PVT1 can reduce the expression of HIF-1α and enhance the sensitivity of gastric cancer cells to DDP." (PMID 32460771, 2020). "PVT1 has been shown to recruit Enhancer of Zeste homolog 2 (EZH2) to epigenetically negatively regulate the expression of p15 and p16 in gastric cancer cell lines." (PMID 32083000, 2020). "In fact, expression of PVT1 and VEGFA in combination predicts poor survival in gastric cancer, further supporting the use of antiangiogenic drugs in these patients." (PMID 32083000, 2020).